PBRM1 (polybromo 1)
Diseases named in the same sentence as PBRM1 in open-access papers (continued):
Sharing a sentence is not in itself a finding about the gene and the disease.
tumor (continued). "Several studies have proved the crucial role of BAP1 and PBRM1 in tumor development." (PMID 35918352, 2022). "PBRM1 loss defines a non-immunogenic tumor phenotype associated with immune checkpoint inhibitor resistance." (PMID 36362284, 2022). "Comprehensive public databases and the data in our group found that the abnormal SWI/SNF subunit PBRM1 was closely related to tumor immune microenvironment-related factors, such as high expression of the immunosuppressive molecules PD-L1 and CTLA4, high sTIL, and iTIL." (PMID 35928964, 2022). "Although patients with tumors harboring a PBRM1 mutation seem to have a shorter DFS versus patients with wild-type tumor, PBRM1 mutations did not appear to differentiate DFS outcomes in treatment-specific arms." (PMID 36216827, 2022). "PBRM1 mutations, TMB and tumour immunophenotypes influence ICI efficacy to some extent." (PMID 36741716, 2022). "They described three types of tumors presenting different growth patterns: VHL inactivation and chromosome 3p loss had an indolent growth course in comparison to those with PBRM1 mutations, while tumours mutated for both BAP1 and PBRM1 presented rapid progression." (PMID 36551652, 2022). "In our study, multivariable models were adjusted for underlying clinical characteristics, which leads us to believe that the protective effects on CSS we observe for mutations in VHL and PBRM1 are independent of underlying tumour characteristics." (PMID 35444164, 2022). "Our observations are consistent with recent reports demonstrating that inactivating mutations of the core components, e.g., PBRM1 of the PBAF complex, that are antagonistic to the PRC2 complex in tumor cells enhanced IFN-γ signaling and sensitized the PBAF-deficient tumors to ICB therapies." (PMID 35852856, 2022). "Moreover, the PBRM1‐deficient cell lines were shown more sensitive to irradiation, and targeted inhibition of c‐JUN can prevent tumour progression caused by PBRM1 deficiency." (PMID 36178086, 2022). "The low expressions of immunomodulatory were seen in subtype 2, consistent with previous finding that PBRM1 loss are associated with a nonimmunogenic tumor phenotype." (PMID 35625960, 2022). "Combined with existing literature, VHL and PBRM1 may also be significantly related to the tumor progression of KIRC and may be used in immunotherapies for treating KIRC." (PMID 35846133, 2022). "Therefore, an abnormal PBRM1 gene can lead to a more favorable tumor microenvironment and make tumor cells more sensitive to immune cell-mediated cytotoxicity, such as that driven by T cells." (PMID 35928964, 2022). "In studying 45 patients (29 PBRM1 tumor wild-type and 16 PBRM1 mutants) from the TCIA using the corticomedullary phase of CT, the random forest classifier outperformed the artificial neural network in predicting tumor genotype, with AUC of 0.987 and 0.925, respectively." (PMID 35159060, 2022). "RCC frequent somatic 3p losses, related to three major RCC tumor suppressor genes, namely VHL (located at 3p25.3), BAP1, and PBRM1 (3p21.1), could have masked germline MITF p.E318K alleles (3p13)." (PMID 34067022, 2021). "Finally, we tested the OS of KIRC patients considering PBRM1 expression and tumor grade at the same time." (PMID 34447697, 2021). "In addition, inactivation of PBRM1 sensitizes tumor cells to T-cell-mediated cytotoxicity and results in a more favorable tumor microenvironment." (PMID 33419967, 2021). "However, it is sufficient to study the effect of PBRM1 on cancer cells and the tumor microenvironment." (PMID 34447697, 2021).
tumor (continued). "Several subunits of the SWI/SNF complex including SNF5 (SMARCB1/INI1/BAF47), ARID1A (BAF240A), SMARCA4 (BRG1), ARID1B (BAF250B), ARID2 (BAF200) and PBRM1 (BAF180) exert critical tumor suppression activities, through inhibiting oncogenic transcription, cell cycle, epigenetic instability and etc.." (PMID 33670012, 2021). "Based on our experimental results, we hypothesized that PBRM1 may affect the chemokines that attract T cells to the tumor microenvironment." (PMID 34447697, 2021). "Next, we analyzed the correlations between tumor grades and PBRM1 expression level." (PMID 34447697, 2021). "The finding is consistent with previous reports indicating deficient PBRM1 in ccRCC to induce a non-immunogenic tumor and resistance to immune checkpoint inhibitors." (PMID 34215851, 2021). "In ccRCC, low expression of PBRM1 and high tumor grade imply a worse prognosis." (PMID 34447697, 2021). "Similarly, we observed that Pbrm1 knockout delayed tumor growth and prolonged survival in our model system." (PMID 32358509, 2020). "PBRM1 inactivation restores the response to immunotherapy by increasing the tumor immunogenicity." (PMID 32708698, 2020). "We also demonstrate that the infiltration of 22 different types of immune cells into the tumor microenvironment is dependent on the status of PBRM1 mutations and independent of VHL mutations." (PMID 33177244, 2020). "Among ERGs that could be classified as tumor suppressors, KMT2D, KMT2C, ARID1A, ATRX, CREBBP, and PBRM1 were frequently mutated in many cancer types, whereas oncogenic ERGs were each mutated in specific cancer types, mainly IDH1 in LGG and DNMT3A in LAML." (PMID 32963031, 2020). "In addition, we identified edges in the tumor GCN that are specific to patients with co-occurring VHL and PBRM1 mutations." (PMID 30814637, 2019). "The role of PBRM1 as tumor suppressor is also supported by the fact that ≈80% of the somatic mutations found in the gene result in loss of function (LOF) of the protein, not only in ccRCC but also in other tumor types, including breast and pancreatic cancers." (PMID 31861590, 2019). "We found that 786‐O PBRM1 knockdown cells generated significantly larger tumors than control cells, consistent with previous reports suggesting that PBRM1 is a potent tumor suppressor that inhibits tumor growth." (PMID 30585695, 2019). "However, a single point mutation in BD2 alone that reduces H3K14ac recognition was sufficient to severely impair PBRM1's molecular and tumor suppressor functions despite maintaining chromatin association." (PMID 30585695, 2019). "Moreover, we showed that PBRM1 displays tumor-progression activity in PCa by enhancing the EMT process and the expression of CSC markers." (PMID 31212728, 2019). "This same tumor also had six variants of uncertain significance: ARID2 c.1672C > T p.(R558C), FLT3 c.2546G > A p.(R849H), IGF1R c.3897C > G p.(N1298K), MSH6 c.1157C > G p.(P386R), PBRM1 c.2504G > A p.(R850H), and RNF43 c.1114C > T p.(P372S)." (PMID 31046843, 2019). "Thus, we think that xenograft analysis is a better tool to assess PBRM1's tumor suppressor function than measuring proliferation in cell culture." (PMID 30585695, 2019). "In summary, in ccRCC the function of PBRM1 as a tumor-suppressor or oncogene is context dependent." (PMID 31861590, 2019). "The study also showed an association of PBRM1 LOF with late tumor stage and worse OS (PBRM1 negative 80 months vs. PBRM1 positive NR (not reached))." (PMID 31861590, 2019). "Multiple lines of evidence suggest that PBRM1 is a key tumor suppressor." (PMID 30355451, 2018). "One of the reasons that this could be such an interesting preventative opportunity is that the region of 3p loss invariably encompasses all four tumor suppressor genes of VHL, PBRM1, BAP1, and SETD2, and hence spans at least 40 Mb." (PMID 29656891, 2018).
tumor (continued). "Thus, our studies reveal that BAF180 function in ccRCC is context dependent, and that mutation of PBRM1/BAF180 serves as an alternative strategy for ccRCC tumors to reduce HIF1 tumor-suppressive activity in H1H2 ccRCC tumors." (PMID 28092369, 2017). "To determine whether PBRM1 expression is correlated with tumorigenesis in vivo, we established a xenograft tumor model." (PMID 28846693, 2017). "It is interesting that PBRM1, BAP1, and SETD2 are all located at chromosome 3p, close to the 3p25 locus, indicating that these tumor suppressors might be functionally linked." (PMID 28846693, 2017). "For example, oncodriveFM missed FLT3 due to a cluster of medium impact mutations and OncodriveCLUST missed several tumor suppressor genes, since loss of function mutations in these genes do not necessarily cluster (e.g. PBRM1)." (PMID 29030609, 2017). "Mutation of PBRM1 is believed to be an early event in carcinogenesis, however its function as a tumor suppressor is not understood." (PMID 27100670, 2016). "ARID1A loss contributes to tumor growth significantly, but it is unlikely to be the major mechanism of tumor suppression by PBRM1." (PMID 27764136, 2016). "Similarly, PBRM1 downregulation correlated with advanced tumor stage, low differentiation grade and worse patient outcome while SETD2 mutations correlated with a high relapse rate." (PMID 28326264, 2015). "Thus, based on the binomial calculation, in order to detect a mutation in PBRM1, SETD2, BAP1, and/or KDM5C with 90% certainty, a tumor would need to be genetically profiled in at least three locations." (PMID 25124064, 2014). "Tumor‐specific factors, such as the immune microenvironment, immune evasion mechanisms, tumor aneuploidy, and the presence of specific mutations (e.g., BRCA1/2, PTEN, PBRM1, or JAK1), all contribute to ICI treatment outcomes, highlighting the necessity for a more comprehensive analysis of the TME." (PMID 40874420, 2025). "The tumor lineage and aggressive potential was confirmed by extensive genetic testing revealing a high tumor mutational burden and pathogenic mutations in TERT, NRAS, and NF1, alongside alterations in PBRM1 and FAT1, which may contribute to the tumor's unique morphology." (PMID 40125165, 2025). "Moreover, PBRM1, which plays a role in anti-tumor immune response, might be a valuable and prospective therapy target." (PMID 41278204, 2025). "The disproportionate impact of Mps1 inhibitors on PBRM1-deficient tumours was also evidenced by the fact that tumour growth of PBRM1 KO-derived tumours, but not that of parental B16-F10 derived tumours, was significantly reduced following treatment with Mps1 inhibitors." (PMID 40011561, 2025). "Additionally, PBRM1 deficiency has been associated with increased expression of MHC II molecules and components of the antigen-processing machinery, potentially improving tumor antigen presentation and amplifying CD8+ T cell responses." (PMID 40963620, 2025). "Therefore, we hypothesised that PD-L1 expression, according to the PBRM1 expression status, could affect perforin and granzyme B mRNA levels by inhibiting the tumour-killing activity of immune cells." (PMID 39375538, 2024). "For our case report, we can speculate, that the PBRM1 mutation was only present in a subfraction of the tumor mass, and thus not all cells were equally susceptible to PARPi." (PMID 37400502, 2023). "To understand the impact of BAP1 deficiency on chromatin accessibility, we used snATAC-seq data to analyze differentially accessible chromatin regions (DACRs) by comparing the tumor cells of BAP1-mutants versus tumor cells from tumors without PBRM1 or BAP1 mutations." (PMID 36973268, 2023). "Therefore, we hypothesized that abnormal PBRM1 may play a role in the carcinogenesis and tumor immune activity of GAC." (PMID 35928964, 2022).
tumor (continued). "PBRM1 and the PBAF complex play a role in the cellular response to DNA damage, and this is a potential mechanism by which IFN signaling could be indirectly affected in PBRM1-deficient tumor cells." (PMID 35902118, 2022). "In our study, neither PBRM1 nor VHL was significantly associated with lower grade tumours." (PMID 35444164, 2022). "For palbociclib, we observed a significant tumor response for one of two models harboring the deletion of CDKN2A/2B (p = 0.02), and no significant tumor response in the PBRM1-mutated PDX; for volasertib, we did not observe any response in the three tested models." (PMID 36505864, 2022). "Importantly, the link between PBRM1 and p21 was preserved in human tumor samples." (PMID 31863007, 2019). "This suggests that even though tumor‐derived point mutations in the BDs of PBRM1 might not grossly alter chromatin association, they are sufficient for the disruption of PBRM1's molecular and tumor suppressor functions." (PMID 30585695, 2019). "While BD2 has been found to bind acetylated histone H3 lysine 14 (H3K14ac), it is not known whether other BDs collaborate with BD2 to generate strong binding to H3K14ac, and the importance of H3K14ac recognition for the molecular and tumor suppressor function of PBRM1 is also unknown." (PMID 30585695, 2019). "On the other hand, if PBRM1 mutations cause response, then loss of PBRM1 mutation might be expected in the post-treatment resistance sample, given tumor heterogeneity in RCC, and we did not observe this." (PMID 30256787, 2018). "Hence it is possible that the finding of PBRM1 mutations in our 5 ccRCC patients correlates with response to rapalog therapy, though not seen in the pre-treatment tumor specimen, rather than representing a mechanism of resistance." (PMID 30256787, 2018). "PBRM1, SETD2 and BAP1, similarly to VHL, map to the 3p21 and this suggests that essential component of ccRCC pathogenesis may be allelic loss of 3p resulting in haploinsufficiency for four tumor suppressors simultaneously." (PMID 28212566, 2017). "Similarly, we observed inter-metastatic tumor heterogeneity of PBRM1 in one (3%) patient." (PMID 28327121, 2017). "Overall, our results suggest that there may be a clone in the primary tumor that had lost PBRM1." (PMID 28327121, 2017). "Re-expression of PBRM1 in BAF180-deficient ccRCC cell lines, both in stable or inducible manner, reduce ccRCC proliferation/survival, further confirming that BAF180 is a tumor-suppressive protein in the BAF180-deficient ccRCC cell lines, which is consistent with published papers." (PMID 28092369, 2017). "Thus ARID1A knockdown seemed to have a more potent tumor-promoting effect than PBRM1 knockdown." (PMID 27764136, 2016). "Besides VHL, other genetic alterations in subgroup-5 involve the mutation of the chromatin remodeling gene PBRM1, the mutation of the histone methyltransferase gene SETD2, which has been identified as a tumor suppressor in KIRC and high methylation rate of GSTP1." (PMID 26148869, 2015). "Interestingly, mutations in PBRM1 and BAP1 were largely observed to occur exclusively, suggesting that simultaneous loss may be disadvantageous to the tumour." (PMID 23016578, 2012). "Although emerging studies are beginning to provide insight, evidence suggests roles for PBRM1, SETD2, and BAP1 in metabolic regulation and in shaping the tumor immune microenvironment in ccRCC." (PMID 41602827, 2026). "Three patients with KRASMUT PDA achieved SD, of whom one had a tumor with ATM defects, and one had SWI/SNF complex alterations in PBRM1 and ARID1B genes." (PMID 40507311, 2025). "In an in situ tumor model constructed in BALB/C mice, the application of ACBL1 in the PBRM1 wild-type group yielded results similar to those of the PBRM1 mutant group, where both promoted immune sensitization to PD1 antibodies in mice." (PMID 40093909, 2025).
tumor (continued). "Emerging research on epigenetic alterations (BAP1, PBRM1, SETD2, CDKN2A) and tumor-stroma interactions is identifying new drug targets, including DNA damage response and CDK4/6 inhibitors, as well as microenvironment-directed therapies such as CSF1R blockade." (PMID 41426798, 2025). "Application of ACBL1, a PROC inhibitor of PBRM1, in BALB/C mice or colorectal patient-derived tumor organoids (PDTOs) significantly promoted the sensitivity to PD1 antibody immunotherapy." (PMID 40093909, 2025). "According to the latest research, variations in the VHL, PBRM1, and SETD2 genes are the strongest evidence for tumor growth and how it responds to therapy." (PMID 41479787, 2025). "Molecular alterations, including chromosomal 3p losses affecting genes such as PBRM1 and BAP1, not only contribute to angiogenesis and tumor progression but also promote an immunosuppressive tumor microenvironment (TME) that facilitates immune evasion." (PMID 40565041, 2025). "The most common gene alterations in the primary tumor in RCC are VHL (64%), PBRM1 (36%), SETD2 (20%), and BAP1 (13%)." (PMID 38386122, 2024). "We next sought to characterize the potential combined anti-tumor effect of PRT1419 and HIF2α inhibitor Belzutifan in PBRM1 mutant ccRCC." (PMID 38371625, 2024). "EBV-miR-BART11 and EBV-miR-BART17-3p promote tumor immune escape by inhibiting FOXP1 and PBRM1 and enhancing PD-L1 transcription." (PMID 39015496, 2024). "Importantly, this multi‐functional nanocarrier could not only enhance the sensitivity of tumor cells against immunotherapy and reduce tumor immune escape via both Pbrm1/PDL1 gene silencing, but also strengthen the cytotoxic activity of immune cells by blocking PD1/PDL1 axis." (PMID 38973319, 2024). "For example, the loss of the 3p chromosome arm disrupts critical genes like VHL, PBRM-1, BRCA1, and MTOR that act as tumor suppressors." (PMID 39796121, 2024). "Alterations in BAP1, PBRM1, and SETD2 are common and important co‐driving factors in tumor development." (PMID 39166457, 2024). "Four tumor suppressor genes map in this region: VHL in 3p.25, PBRM1 (subunit of the PBAF SWI/SNF chromatin remodeling complex), BAP1 (histone deubiquitinase), and SETD2 (histone methyl transferase) in 3p.21." (PMID 36902045, 2023). "This is reasonable given that this chromosome contains four tumor-suppressor genes (VHL, PBRM1, BAP1, and SETD2) that are crucial for cellular survival." (PMID 37842234, 2023). "In many human cancers, the expression of PBRM1 and ARID2 enhances the sensitivity of tumor cells to T cell killing, thereby inhibiting tumor progression." (PMID 37192179, 2023). "A recently accepted notion of RCC progression is that VHL mutation function as an initial event to drive tumorigenesis, while PBRM1, BAP1 and SETD2 subsequent trigger defects in DNA repair system and abnormal tumor growth." (PMID 37064095, 2023). "To carry out such a multilevel investigation, we measured the mRNA levels of VHL, SETD2, PBRM1 and BAP1 genes by qPCR on the same tumour-normal paired sample set used for our CNV characterisation." (PMID 35586183, 2022). "This study sought to explore the relationship between PBRM1 gene abnormalities and the occurrence and development of GAC and tumor immune activity and to provide evidence for its potential use as a predictive marker for GAC immunotherapy." (PMID 35928964, 2022). "In this paper, cBioPortal, LinkedOmics and TISIDB datasets were used to analyze the abnormality of the PBRM1 gene in GAC and its relationship with prognosis, related molecular changes and tumor-infiltrating lymphocytes (TIL)." (PMID 35928964, 2022). "It has been found that PBRM1 modulates HIF1a-VEGF signal and STAT3-Interferon signal and BAP1 promotes genomic instability and therefore accelerates tumor metastasis." (PMID 35439951, 2022).